CGAS (cyclic GMP-AMP synthase)
Diseases named in the same sentence as CGAS in open-access papers (continued):
Sharing a sentence is not in itself a finding about the gene and the disease.
cancer (continued). "Further investigation of the mechanism of epigenetic silencing of cGAS may lead to the development of more potent and specific compounds that restore cGAS expression as anti-cancer agents." (PMID 41509453, 2026). "The role of the cGAS-STING in cancer immunity varies greatly across cancer types." (PMID 40052963, 2025). "Triggering the cGAS-STING pathway holds potential for cancer therapy." (PMID 41007720, 2025). "Additionally, mitochondria-localized cGAS promotes cancer progression by suppressing ferroptosis in a manner dependent on an increase in DRP1 oligomerization instead of the canonical cGAS-STING pathway." (PMID 40083691, 2025). "Decreased cGAS or STING expression was observed in several cancer cell lines." (PMID 40552295, 2025). "In the past decade, interest has increased in elucidating the role of cGAS-STING in cancers." (PMID 40552295, 2025). "cGAS-STING signaling pathway offers immense potential for revolutionizing cancer immunotherapy." (PMID 40052963, 2025). "The cGAS-STING pathway is a critical component of innate immune responses against cancer." (PMID 41417876, 2025). "Cancer cells can reprogram astrocytes via the cyclic GMP-AMP synthase (cGAS)-Stimulator of Interferon Genes (STING) pathway by transferring 2′,3′-cyclic GMP-AMP (cGAMP), leading to the production of inflammatory cytokines such as interferon-α (IFN-α) and tumor necrosis factor-α (TNF-α)." (PMID 40136375, 2025). "Besides the PD-1/PD-L1 pathway, the cGAS-STING pathway is another critical signal transduction route in cancer immunotherapy." (PMID 39861694, 2025). "Developed by Professor Jin Jian and Professor Wenyi Wei, the first-in-class deubiquitinase-targeting chimeras (DUBTACs) of cGAS MS7829 and MS8588 stabilize and activate cGAS, effectively inhibiting cancer cell growth by enhancing the cGAS-STING signaling pathway." (PMID 40028324, 2025). "The cGAS‐STING signaling pathway has emerged as a promising target for cancer immunotherapy." (PMID 40568953, 2025). "The cGAS/STING pathway is crucial in the immune response of cancer cells exposed to radiation." (PMID 40740877, 2025). "There have been considerable challenges in targeting the cGAS-STING pathway for cancer treatment." (PMID 40052963, 2025). "PRMT1 has been implicated in enhancing immune evasion, suggesting that investigations into cGAS methylation may provide novel insights into the mechanisms of cancer immunology." (PMID 40470467, 2025). "Some studies demonstrate that persistent activation of the cGAS-STING pathway in CRC may lead to downstream signal rewiring in cancer cells, thereby fostering a pro-metastatic TME." (PMID 41041344, 2025). "Further findings offer mechanistic insights into the dual role of FOXO proteins in autophagy mediated cancer progression and present potential components for the development of personalized therapeutic strategies aimed at targeting the cGAS–STING–FOXO–autophagy axis." (PMID 41378291, 2025). "Furthermore, deletion or inactivating mutations in the C-terminal region of TREX1 in chromosomally unstable cancer cells disrupted micronuclear DNA degradation and increased cGAS activation." (PMID 40581636, 2025). "A growing body of evidence has shown that cGAS-STING interacts with ferroptosis in cancer cells." (PMID 40846966, 2025). "Notably, the activation of this pathway in cancer cells facilitates antigen cross-presentation and T-cell responses by enabling the transfer of cGAS-STING signaling from cancer cells to antigen-presenting cells (APCs)." (PMID 40282455, 2025). "Moreover, high-dose irradiation had differential effects on the cGAS/STING signaling pathway transcript levels in the two cancer cell lines." (PMID 41007670, 2025). "Next, we queried cGAS-STING target gene expression among the patients who respond or do not respond to immune checkpoint inhibitors using the ROC Plotter server that includes all types of cancer." (PMID 41193733, 2025).
cancer (continued). "The cGAS-STING signaling pathway also plays a dual role in the development of cancer." (PMID 40362284, 2025). "Pharmacological activation of the cGAS-STING pathway might be a promising strategy for cancer immunotherapy." (PMID 41380972, 2025). "The cGAS-STING pathway plays a pivotal role in cancer defense, particularly in tumors with CIN." (PMID 40052963, 2025). "For instance, nuclear cGAS anchors to chromatin and suppresses homologous recombination‐mediated DNA repair in response to genotoxic stress‐induced DNA damage, thereby directly promoting cancer cell proliferation independently of STING." (PMID 39737867, 2025). "Emerging compounds activating cGAS-STING for cancer treatment." (PMID 40552295, 2025). "Notably, emerging evidence indicates that the cGAS-STING pathway plays a significant role in mediating cellular senescence in cancer cells." (PMID 40621423, 2025). "Thus, the activation of the cGAS-STING pathway has become the subject of numerous studies in the field of cancer therapy." (PMID 39857957, 2025). "Thus, pharmacological targeting of the cGAS-STING-ferroptosis pathway represents a novel therapeutic strategy for cancer." (PMID 40846966, 2025). "Moreover, high methionine flux also supports the cancer cells to evading pyroptosis, which maintains the genome-wide hypermethylation that regulates the genes refer to metal ion transporter, SMADs, and cGAS-IFN-1 signaling cascade." (PMID 41445748, 2025). "Recent studies have highlighted the pivotal role of the cGAS‐STING pathway in cancer immunotherapy." (PMID 40548883, 2025). "The cGAS-STING pathway was reported to have dual effects in cancers." (PMID 40786100, 2025). "The outcomes of the cGAS-STING pathway in cancers are target-dependent." (PMID 40786100, 2025). "PD-L1 constitutively activates cGAS-STING-IFNβ in cancer cells with chronic DNA damage." (PMID 39747659, 2025). "The cGAS-STING pathway has been implicated in various stages of the cancer immune cycle, such as inducing cancer cell death, enhancing antigen processing and presentation, promoting T cell activation and tumor infiltration, and facilitating T cell recognition and clearance of cancer cells." (PMID 40006592, 2025). "In addition, when cGAS and STING were deficient, the chemotactic migration of macrophages by mechanic compressed carcinoma cells was impaired." (PMID 39737867, 2025). "In addition, inhibition of cGAS activity in carcinoma cells attenuates inflammatory cell infiltration and ameliorate VHPV liver metastasis, blocking splenocyte to migrate into liver show a similar effect as the cGAS inhibition." (PMID 39737867, 2025). "Considering that cell compression induced cGAS activation and resulted in chemokines expression, the damaged carcinoma cells may remodel the inflammatory niche and thus alter the fate of these cells." (PMID 39737867, 2025). "Furthermore, compared to control cells in vitro, carcinoma cells exhibited a higher proportion of cGAS‐GFP foci‐positive signals in liver capillaries." (PMID 39737867, 2025). "This hypothesis is supported by evidence that cGAMP, the product of cGAS, suppresses cancer cell proliferation and increases anticancer activity." (PMID 39424777, 2024). "The study introduced a novel technique called Contact Tracing for single-cell RNA sequencing data analysis, revealing that chronic CIN-induced activation of the cGAS-STING pathway fosters downstream signaling reconnection in cancer cells, thereby establishing a pro-metastatic TME." (PMID 38817608, 2024). "The cGAS-STING pathway can modulate various stages of the cancer-immunity cycle." (PMID 39170700, 2024). "A number of in vivo studies imply that the cGAS–STING pathway may have protective effects against cancer." (PMID 39125448, 2024). "The crosstalk between autophagy and the cGAS-STING pathway impacts a wide variety of cellular processes such as protection against pathogenic infections as well as signaling in neurodegenerative disease, autoinflammatory disease and cancer." (PMID 38660307, 2024).
cancer (continued). "Similarly, in some studies cGas expression in DC is necessary for immune responses, while in other studies cGas expression in cancer cells is necessary, meaning that the origin and therefore transmission of cGAMP is of unclear importance." (PMID 39622844, 2024). "Therefore, it will be of interest to extend the field of application of drugs targeting cGAS or STING developed for cancer immunotherapy as novel regulators of senescence cell fate." (PMID 38561826, 2024). "A pan-cancer analysis revealed that high activation of the cGAS-STING pathway and its downstream signaling components such as TBK1 and IRF3 is associated with reduced immune cell infiltration in the TME and poor prognosis for colorectal and gastric adenocarcinomas." (PMID 38999073, 2024). "Furthermore, cGAS/STING signaling dysregulation in cancer patients’ myeloid immune cells (MICs) increases the cancer’s severity." (PMID 38339107, 2024). "Therefore, high cGAS expressed cancer cells enhances lymphocytes transendothelial migration by activation of endothelial STING, rather than lymphocytes STING pathway, through cGAMP secretion." (PMID 38177099, 2024). "Cancer cells treated with DNA-damaging agents may release DNA fragments or other immunogenic molecules to activate the cGAS-STING pathway in neighboring antigen-presenting cells (APCs)." (PMID 38332843, 2024). "As a case in point, Mn2+ plays a crucial role in regulating the host's immune system 14, e.g., Mn2+ can promote dendritic cell (DC)-mediated cancer immunotherapy by stimulating the cGAS-STING (cyclic guanosine monophosphate-adenosine monophosphate synthase-stimulator of interferon genes) pathway." (PMID 38994034, 2024). "Recent studies have revealed the multiple role of cGAS-STING pathway in cancer." (PMID 38510490, 2024). "Recently, cGAS-STING pathway has become a hot spot in cancer immunotherapy, since STING agonists can synergize with other cancer immunotherapies, including cancer vaccines, immune checkpoint inhibitors and adoptive T cell transfer, to boost the anticancer immunity in advanced cancer treatment." (PMID 38773213, 2024). "Additionally, the discovery of the cGAS-STING pathway has revealed novel avenues in cancer treatment, with STING agonists displaying remarkable potentials." (PMID 38512518, 2024). "In addition, cytosolic DNA generated from viral DNA and chromosomal instability of cancer is thought to trigger the cyclic GMP-AMP synthase (cGAS) stimulator of interferon genes (STING) pathway." (PMID 38610990, 2024). "Activating the cGAS‐STING pathway is considered a promising approach for fighting against cancer." (PMID 39183480, 2024). "Activation of cGAS-STING pathway is promising therapeutic approach for cancer immunotherapy." (PMID 38832958, 2024). "In addition to the direct effects, the cGAS–STING signaling pathway also plays an important role in inducing cancer cell senescence and apoptosis." (PMID 38525112, 2024). "Several reports indicated that cGAS/STING signalling is frequently suppressed in cancers." (PMID 39049995, 2024). "Therefore, major efforts are ongoing to develop more potent and selective cGAS-STING agonists to boost cancer immunotherapy." (PMID 38177099, 2024). "Moreover, the cGAS/STING signaling pathway is frequently suppressed or inactivated in a variety of cancers, including CRC." (PMID 39469633, 2024). "Interestingly, low, basal levels of type I IFN expressed in cancer cells have accounted for enhanced immunity in response to immunotherapies that is driven by DNA leakage and cGAS/STING." (PMID 38912586, 2024). "Elevated TREX1 expression has also been observed in response to chemotherapeutics and ionizing radiation in various cancer cell types resulting in decreased levels of cytosolic dsDNA, diminished activation of the cGAS-STING pathway, and consequent reduction of Type-I IFN secretion." (PMID 39178223, 2024).
cancer (continued). "To assess whether our findings about Senataxin and EXO1 roles in cGAS positive MN production could influence the pathogenesis of human cancer, we studied the expression of these two proteins in different publicly available data sets in the TCGA repository." (PMID 39120648, 2024). "cGAS activation is also a target for immunoevasion in cancer." (PMID 38675916, 2024). "More importantly, STING can be activated by cGAS through the second messenger cGAMP of cyclic dinucleotide (CDN).The established cGAS-STING pathway plays an important role in connecting anti-cancer innate immunity and adaptive immunity, thereby offering a novel strategy for the treatment of NSCLC." (PMID 38566036, 2024). "The expression of the cGAS-STING cascade response in the peripheral blood CD8+ T cells of cancer patients was significantly impaired, which may also be related to the poor prognosis of patients." (PMID 39464890, 2024). "Indeed, activation of the cGAS-STING pathway not only induces IFN-I for participation in the cancer immune cycle but also exhibits unique characteristics." (PMID 38512518, 2024). "Additionally, chronic activation of the cGAS-STING pathway induced by CIN leads to a reorganization of downstream signaling in cancer cells." (PMID 38523155, 2024). "The cGAS-STING signaling pathway has attracted significant attention in cancer immunotherapy." (PMID 39185402, 2024). "Besides aberrant DNA sources, other potential DNA origins also play a role in triggering the cGAS-STING pathway in cancer." (PMID 39420203, 2024). "Chronic low-grade inflammation is one of several factors predisposing humans to developing cancers, and chronic low-grade type 1 IFN generation through the activation of cGAS/STING signaling promotes tumorigenesis and its further spread and proliferation, as discussed in detail elsewhere." (PMID 38339107, 2024). "Therefore, we can state that the effects of cGAS/STING pathway potentiation should be analysed according to the molecular features of human cancers." (PMID 39215193, 2024). "Additionally, radiation triggered MHC upregulation for driving the broader antigen presentation and activated dsDNA-mediated cGAS/STING-dependent type I IFN production to enhance cancer immunogenicity." (PMID 38821980, 2024). "The discovery of how the cyclic GMP-AMP synthase/stimulator of interferon (IFN) genes/IFN (cGAS/STING/IFN) pathway augments antitumor immunity via enrichment of an immune-suppressive TME may lead to further breakthroughs in cancer immunotherapy." (PMID 38502231, 2024). "Svg3, a cGAS-specific ODN agonistic, has been found to activate cGAS and may prove useful as an anti-cancer immunotherapy." (PMID 39050748, 2024). "Targeting the cGAS crotonylation–decrotonylation cycle could be a novel approach to sensitize cancer cells to radiation and chemotherapeutic agents, especially in cancers characterized by impaired DDR pathways." (PMID 39002667, 2024). "The phosphorylated cGAS can involve in chromatin remodeling by incorporation into chromatin, resulting in the formation of relaxed form of chromatin, resulting in increase of cell transformation and cancer cell proliferation." (PMID 39424777, 2024). "Our results support a cancer model whereby TREX1 upregulation is associated with chemotherapy resistance, as well as resistance to chemoimmunotherapy or ICB therapies by suppressing cGAS-STING-dependent innate immune response." (PMID 39177280, 2024). "Moreover, cancer cell-intrinsic activation of cGAS promotes antitumor immunity, which is critical for the full therapeutic effect of STING agonists and of certain chemotherapy drugs." (PMID 38482021, 2024). "This suggests that targeted activation of the cGAS-STING pathway could serve as a promising strategy for cancer immunotherapy." (PMID 39669992, 2024).
cancer (continued). "Recent reports have linked the cGAS-STING pathway with autophagy, revealing multiple regulatory mechanisms and interactions that highlight the potential of exploiting these pathways for cancer therapy." (PMID 38660307, 2024). "Given its easy availability and extensively researched toxicity, Mn2+ could be an attractive option to augment NK cell‐based cancer immunotherapy as it acts as a pan‐agonist of cGAS and STING." (PMID 39206412, 2024). "Furthermore, although high expression of cGAS or STING predicts poor outcomes for cancer patients, downregulation of this axis has been proposed as an immune escape strategy employed by cancer cells." (PMID 39043779, 2024). "Due to selective pressure, surviving cancer cells often have defects in the cGAS-STING pathway." (PMID 39403369, 2024). "Therefore, the intact cGAS-STING is an important regulator of cancer cell growth and immune surveillance." (PMID 39403369, 2024). "Understanding these dynamics could pave the way for more effective and targeted cancer therapies, leveraging the intricate interplay of the cGAS-STING pathway in different cellular contexts." (PMID 38523155, 2024). "Recently, the role of the cGAS-STING pathway in cancer has garnered significant attention." (PMID 39439455, 2024). "Collectively, these data suggest that T-DXd may modulate DC function in a cancer cell-dependent manner, particularly through the cGAS-STING-IFN-I axis." (PMID 39449023, 2024). "Numerous research studies have linked a poor prognosis in human cancers to the inhibition of the cGAS-STING pathway, as the lack of cytosolic DNA detection contributes to immune escape in cancer cells." (PMID 38817608, 2024). "This suggests that an increase in cGAS-STING signaling may predict poorer outcomes in cancer patients." (PMID 38545114, 2024). "In the realm of cancer, the cGAS-STING pathway plays a pivotal role in facilitating a variety of functions that may sometimes be conflicting." (PMID 39420203, 2024). "While persistent cGAS/STING activation promotes chronic inflammation, a hallmark of cancer." (PMID 39403376, 2024). "Commonly, RSK2 and cGAS strongly involves in the chromatin remodeling that affects gene expression involved in DNA repair, cell cycle regulation, and NF-κB-mediated inflammation and immune responses, which act as important factors in cancer development." (PMID 39424777, 2024). "In addition, immature DCs take up cancer cell-derived dsDNA, leading to the activation of their own cGAS-STING axis within immature DCs." (PMID 38474078, 2024). "Accumulation of double strand DNA (dsDNA) in the cytoplasm of senescent cancer cells leads to the activation of the stress sensor pathway mediated by the cyclic guanosine monophosphate-adenosine monophosphate (cGAMP) synthase (cGAS) and the adaptor stimulator of interferon genes (STING)." (PMID 38561826, 2024). "Therefore, the antitumor effect of a cancer vaccine can be increased by combining it with cGAS–STING agonist treatment." (PMID 38525112, 2024). "In addition to this, it is also important to highlight the recurrent inactivation of cGAS/STING pathway in a wide variety of cancers suggesting a potential additional immune escape mechanism driven by modulation of the cGAS/STING pathway." (PMID 38561826, 2024). "Alternatively, cGAS activation in cancer EV-treated cells can be driven by DNA damage and leakage of genomic DNA to the cytosol, which may also lead to senescence, as observed in this study and by others." (PMID 38530366, 2024). "Thus, we aimed to summarize the novel mechanisms underlying cGAS-STING-IFN-I signal activation in DC-mediated antigen presentation and its role in the cancer immune cycle in this review." (PMID 38512518, 2024). "Crucially, aside from immune cells, cells of the non-immune stromal compartment, such as cancer-associated fibroblasts (CAFs) and endothelial cells, also act as key mediators and effectors of cGAS–STING signalling in the TME." (PMID 36876871, 2023).